SETDB1 (SET domain bifurcated histone lysine methyltransferase 1)
Diseases named in the same sentence as SETDB1 in open-access papers (continued):
Sharing a sentence is not in itself a finding about the gene and the disease.
acute myeloid leukemia (13 papers, 2018 to 2025). Acute myeloid leukemia (AML) is a group of neoplasms arising from precursor cells committed to the myeloid cell-line differentiation. "SETDB1 loss in acute myeloid leukemia (AML) cell leads to retroelement reactivation, which leads to apoptosis through a cytosolic dsRNA-sensing pathway." (PMID 32486217, 2020). "On the contrary, SETDB1 inhibits the expression of genes associated with acute myeloid leukemia (AML), such as Dock1, Hoxa9, and Six1, to delay MLL-AF9-mediated disease progression by promoting the differentiation of leukemia cells." (PMID 38057834, 2023). "As a histone methyltransferase, SETDB1 was first found to keep silencing the transposable elements (TEs) that lead to the production of dsRNAs in acute myeloid leukemia (AML)." (PMID 36600243, 2023). "Knock out of SETDB1 in acute myeloid leukemia (AML) cell lines triggered the expression of retrotransposable elements, production of dsRNAs, and the activation of viral defense-related genes." (PMID 34968293, 2020). "For instance, SETDB1 knockdown induces apoptosis in acute myeloid leukemia (AML) cells through immune response pathways, underscoring its oncogenic role." (PMID 39764697, 2025). "This protective mechanism in healthy tissue may be usefully subverted in cancer: indeed, in acute myeloid leukemia and solid tumor models – both characterized by aberrant DNA methylation – depletion of MPP8 or HUSH effector SETDB1 caused activation of tumor-suppressive transposons." (PMID 39214989, 2024). "SETDB1 functions as a tumor suppressor in Acute Myeloid Leukemia (AML) by promoter histone methylation and repression of tumorigenic genes, such as Sineoculis homeobox homolog 1 (Six1), HoxA9 and Dedicator of Cytokinesis 1 (Dock1)." (PMID 34440561, 2021). "On the other hand, SETDB1 inhibits ERV expression through H3K9 methylation to prevent ERV-induced B cell immune response, thereby enabling acute myeloid leukemia (AML) cells to evade innate immunity." (PMID 39583200, 2024). "In acute myeloid leukemia (AML), Cuellar and colleagues demonstrated that the silencing of H3K9 methyltransferase SETDB1 leads to the overexpression of different TEs, promoting IFN antiviral response through dsRNA-sensing pathway." (PMID 32366056, 2020). "Similarly, in acute myeloid leukemia, SETDB1 has been found to function as a novel negative innate immune regulator by suppressing type I interferon response, thereby contributing to immune evasion and oncogenic cellular state." (PMID 38057834, 2023).
bladder cancer (12 papers, 2014 to 2025). "In bladder cancer, circPTK2 enhances the stability of SETDB1 mRNA by binding to PABPC1, subsequently facilitating SETDB1 expression." (PMID 38664370, 2024). "For example, circPTK2 binds to PABPC1 and enhances its ability to stabilize SETDB1 mRNA, thus promoting tumor metastasis and gemcitabine resistance in bladder cancer." (PMID 39143552, 2024). "Additionally, CircPTK2 interacts with PABPC1 and enhances SETDB1 mRNA expression, thereby facilitating gemcitabine resistance in bladder cancer." (PMID 39866227, 2025). "CircPTK2/PABPC1/SETDB1 pathway promotes metastasis and gemcitabine resistance of bladder cancer." (PMID 38664370, 2024). "In bladder cancer, circPTK2 binds to PABPC1 and stabilizes SETDB1 mRNA to promote its expression, facilitating SETDB1‐mediated EMT and gemcitabine resistance." (PMID 39901896, 2025). "CircRNA PTK2 enhances the stability of SETDB1 and accelerates SETDB1-induced EMT in bladder cancer." (PMID 40703656, 2025). "Additionally, circPTK2 can bind to PABPC1 and stabilize SETDB1 mRNA, thereby promoting SETDB1 expression, EMT, and metastasis in bladder cancer." (PMID 40612865, 2025).
liver cancer (11 papers, 2015 to 2026). An epithelial or non-epithelial malignant neoplasm that arises from the liver. "To investigate the biological consequences of SETDB1 overexpression, we conducted ssGSEA using curated gene signatures associated with poor prognosis in liver cancer." (PMID 41493679, 2026). "For example, SETDB1 can interact with Tiam1 to promote its expression, and further promote the progression of liver cancer." (PMID 38317200, 2024). "In colon, lung, and liver cancers, SETDB1 methylated and silenced T53 in the promoter region, but apoptosis was stimulated in SETDB1 knockdown cells." (PMID 31768101, 2019). "From these experiments, we conclude that SETDB1 is overexpressed in a subset of liver cancer patients." (PMID 26471002, 2015). "Our findings suggest that SETDB1 promotes liver cancer cell growth, which depends on its methylation enzymatic activity." (PMID 26471002, 2015). "To corroborate these results, we assayed the expression of SETDB1 in six independent pairs of liver cancer samples with adjacent normal tissue as the control using reverse transcriptase quantitative PCR (RT–qPCR)." (PMID 26471002, 2015). "To assess the protein levels of SETDB1 in liver cancer samples, we performed immunocytochemistry using tumour tissue microarray (TMA) with an antibody against SETDB1." (PMID 26471002, 2015). "We observed that SETDB1 is expressed in different cell types in both subtypes of liver cancer." (PMID 41493679, 2026). "On the other hand, it also suggests that the development of SETDB1 inhibitors with high specificity, low toxicity and high efficiency may provide a new option for SETDB1 targeted liver cancer treatment." (PMID 39583200, 2024). "Another study found that SETDB1 could affect the biological behavior of liver cancer cells by regulating the methylation status of certain key genes." (PMID 39583200, 2024). "Consistently, miR-29a also negatively regulated the SETDB1 mRNA and protein levels in liver cancer." (PMID 30054425, 2018). "Besides, amplification of the SETDB1 gene was found in lung and liver cancers, and SETDB1 and SUV39H1 were negatively regulated by miR-29 and miR-125b, respectively." (PMID 27572307, 2016). "At present, SETDB1 inhibition has been shown to significantly improve the sensitivity of liver cancer radiation therapy, so combining SETDB1 inhibition with the currently used liver cancer treatment methods, such as chemotherapy, radiotherapy or gene therapy, may have a good therapeutic effect." (PMID 39583200, 2024). "We next asked whether SETDB1 is overexpressed in liver cancer." (PMID 26471002, 2015). "The H3K9 tri-methyltransferase genes, SETDB1 and SUV39H1, have been shown to be overexpressed in cancers, such as lung and liver cancers." (PMID 27572307, 2016). "We surveyed publicly available gene expression data and found that SETDB1 is highly expressed in various tumour types including breast, renal cell cancer (RCC) and liver cancers." (PMID 26471002, 2015).
gastric cancer (9 papers, 2015 to 2025). A primary or metastatic malignant neoplasm involving the stomach. "SETDB1 is induced by H. pylori infection through TCF4, suggesting a mechanism for this infection, which is associated with gastric cancer, to promote cell proliferation." (PMID 41425714, 2025). "SETDB1 mediates the malignant biological behaviour of gastric cancer by interacting with ERG and enhancing the promoter activity of CCND1 and MMP9." (PMID 38317200, 2024). "The Cancer Genome Atlas database data indicate that SETDB1 is significantly upregulated in various cancers including colorectal, liver, and gastric cancer." (PMID 37541664, 2023). "Moreover, Kaplan–Meier analysis demonstrates that high SETDB1 expression is positively correlated with poor survival outcomes in colorectal and gastric cancer patients." (PMID 37541664, 2023). "High expression of SETDB1 was also identified in gastric cancer." (PMID 35159180, 2022). "Similarly, Helicobacter pylori (H. pylori) infection induces SETDB1 expression in a TCF4-dependent manner, which contributes to gastric cancer formation." (PMID 38057834, 2023). "Thus, SETDB2 expression and function detected in our study were similar to those of SETDB1 and SUV39H1 in cancers, suggesting that SETDB2 may have oncogenic functions and overexpression of SETDB2 play roles in gastric cancer progression." (PMID 27572307, 2016).
glioma (9 papers, 2015 to 2023). A benign or malignant brain and spinal cord tumor that arises from glial cells (astrocytes, oligodendrocytes, ependymal cells). "It is reported that the protein levels of H3K9me3 and SETDB1 were increased in patients with pediatric high-grade gliomas." (PMID 38057834, 2023). "Suppression of SETDB1 was shown to affect cell proliferation, migration, and colony formation of glioma cells." (PMID 36139694, 2022). "SETDB1 expression was found upregulated in glioma cell lines and glioma tissues compared to a normal brain, and it was positively correlated with tumor grades and histological type." (PMID 36139694, 2022). "Overexpression of SETDB1 also promotes G1/S phase transition in nasopharyngeal carcinoma, while suppression of SETDB1 reduces the cell migratory and clonogenic ability in glioma cells." (PMID 35159180, 2022). "Increased nuclear SETDB1 expression has been detected in glioma tissues and correlates with high histological grades, as well as enhanced resistance to chemotherapeutic drugs." (PMID 34440561, 2021). "Small interfering RNAs (siRNAs) or histone methyltransferase inhibitors that inhibit SETDB1 have been applied in glioma cell lines and significantly decrease cell proliferation and migration while promoting apoptosis." (PMID 34440561, 2021). "Experimental data implicates histone H3 lysine (K) methyltransferases SETDB1 and SUV39H1 into glioma pathobiology, whereas linker histone variant H1.0 and H4K20me3 reportedly affect prognosis." (PMID 25602259, 2015).
non-small cell lung carcinoma (8 papers, 2018 to 2023). A group of at least three distinct histological types of lung cancer, including non-small cell squamous cell carcinoma, adenocarcinoma, and large cell carcinoma. "Up to now, we do not have a clear explanation of this phenomenon, however, the correlation of the overexpression of naive SOD1 has been documented in the non-small cell lung cancer where the rate of proliferation was associated with the activity of miR-409-3p/SOD1/SETDB1 pathways." (PMID 34572266, 2021). "miR-409-3p has been reported to negatively regulate the expression of SETDB1 in non-small cell lung cancer (NSCLC)." (PMID 38057834, 2023). "Here, we investigated the clinical significance of SETDB1 expression in the two major forms of human non-small cell lung carcinoma (NSCLC), i.e., adenocarcinoma (ADC) and squamous cell carcinoma (SCC), by combining a meta-analysis of transcriptomic datasets and a systematic review of the literature." (PMID 31398867, 2019).
ovarian carcinoma (8 papers, 2019 to 2025). A malignant neoplasm originating from the surface ovarian epithelium. "Therefore, we speculate that SETDB1 may be involved in vascular remodeling in ovarian cancer and associated with epithelial-mesenchymal transformation." (PMID 38317200, 2024). "Mechanistically, SETDB1 knockout in ovarian cancer led to mitotic defects, micronuclei formation, and upregulation of PD‐L1 via the cGAS‐STING pathway." (PMID 39764697, 2025). "Results of the present study confirmed that SETDB1 expression was upregulated in ovarian cancer and its high expression predicted poor prognosis." (PMID 38317200, 2024). "In this study, we found an amplification of the SETDB1 methylation site in ovarian cancer, and the upregulation of SETDB1 decreased the expression of multiple immune cells." (PMID 38317200, 2024). "In our study, we found that SETDB1 was over-expression in ovarian cancer, and its upregulation was related to poor PFS, OS and PPS of OC patients." (PMID 38317200, 2024). "In ovarian cancer, the increased expression of SETDB1 was accompanied by a decreased abundance of multiple immune cells." (PMID 38317200, 2024). "The results revealed that the expression of SF3B4 mRNA decreased notably after SETDB1 knockdown in ovarian cancer cells." (PMID 38317200, 2024). "Although we validated that SETDB1 promoted ovarian cancer progression by promoting the transcription of SF3B4, our study still has several limitations." (PMID 38317200, 2024). "The mechanism by which SETDB1 affects the microenvironment of ovarian cancer needs to be further studied." (PMID 38317200, 2024). "SETDB1 promoted ovarian cancer progression by upregulating the expression of SF3B4 and inhibiting the tumour immunity." (PMID 38317200, 2024). "In summary, our study verified that SETDB1 was up-regulated and associated with poor PFS, OS and PPS in ovarian cancer patients." (PMID 38317200, 2024). "SETDB1 binding to SMAD3 methylates and suppresses T cell receptor-induced IL-2 transcription, presenting an additional mechanism of SETDB1 involvement in ovarian cancer tumorigenesis." (PMID 34440561, 2021). "For cervical cancer, therapies targeting MLL2 or m5C regulators like NSUN2 could restore immune recognition, while in ovarian cancer, inhibiting SETDB1 or KDM5A could enhance T-cell responses." (PMID 41029427, 2025). "Similarly, SF3B4 knockdown also impaired the effect of SETDB1 to promote the mobility of ovarian cancer cells." (PMID 38317200, 2024). "Finally, the results of bioinformatics analysis confirmed that SETDB1 regulated the immune microenvironment of ovarian cancer." (PMID 38317200, 2024). "Importantly, the expression of SETDB1 was related to clinical stage and grade in ovarian cancer patients." (PMID 38317200, 2024). "We found SETDB1 may regulate the microenvironment of ovarian cancer and affect epithelial-mesenchymal transformation and immunity through bioinformatics analysis." (PMID 38317200, 2024). "The KAP1/SETDB1 complex plays a crucial role in suppressing antitumor immunity in ovarian cancer." (PMID 39519018, 2024). "Therefore, our results confirmed that SETDB1 promotes the migration and invasion of ovarian cancer cells." (PMID 38317200, 2024). "However, the exact mechanism of SETDB1 in ovarian cancer progression remains to be further researched." (PMID 38317200, 2024). "It is well known that recurrence and drug resistance are the difficulties in ovarian treatment, whether SETDB1 is involved in chemotherapy resistance of ovarian cancer and its mechanism need to be further explored." (PMID 38317200, 2024). "Although SETDB1 has been reported to play an important role in several tumours, the mechanism by which SETDB1 regulates ovarian cancer progression remains unclear." (PMID 38317200, 2024). "Moreover, SETDB1 was involved in regulating the immune microenvironment in ovarian cancer." (PMID 38317200, 2024). "Therefore, SETDB1 plays a cancer-promoting effect in ovarian cancer." (PMID 38317200, 2024).
ovarian carcinoma (continued). "SETDB1, a H3K9 methyltransferase, is overexpressed in ovarian cancer and promotes tumor progression by silencing tumor suppressor genes and inhibiting antitumor immune responses." (PMID 41029427, 2025). "In ovarian cancer, histone methylation regulates the TIME and immunotherapy efficacy through the actions of methyltransferases like SETDB1 and demethylases like KDM5A." (PMID 41029427, 2025). "However, the effect of SETDB1 protein in ovarian cancer remains unclear." (PMID 38317200, 2024). "Kaplan‒Meier analysis showed that the higher expression of SETDB1 predicted poor progression-free survival (PFS) and poor post-progression survival (PPS) in ovarian cancer patients." (PMID 38317200, 2024). "In advanced ovarian cancer, TGF-β- induced epigenetic silencing of epithelial genes, including CDH1, is mediated through SETDB1, leading to EMT and metastasis." (PMID 34440561, 2021).